APCDD1 (APC down-regulated 1)
Description:
Negative regulator of the Wnt signaling pathway. Inhibits Wnt signaling in a cell-autonomous manner and functions upstream of beta-catenin. May act via its interaction with Wnt and LRP proteins. May play a role in colorectal tumorigenesis.
Synonyms: DRAPC1; FP7019; B7323; HHS; HTS; HYPT1
Tractability: Antibody: UniProt places it where antibodies can reach, with high confidence; its Gene Ontology location is reachable by antibodies, with high confidence; UniProt predicts a signal peptide or a membrane-spanning region.
Gene: Protein-coding gene on chromosome 18 (10,454,635 to 10,489,949, forward strand). Ensembl gene ENSG00000154856.
Subcellular location: Cell membrane
Gene Ontology:
Molecular function: identical protein binding; protein binding; Wnt-protein binding
Biological process: hair follicle development; negative regulation of Wnt signaling pathway; regulation of odontogenesis of dentin-containing tooth
Cellular component: plasma membrane
Genetic constraint (gnomAD): Loss-of-function variants: 16 observed, 41.48 expected, observed/expected ratio (o/e) 0.39, 90% interval 0.26 to 0.59. The upper end of that interval is the gene's LOEUF score, 0.59, which puts it in group 2 of 6, group 1 being the genes least tolerant of losing a copy. Missense variants: 647 observed, 720.51 expected, observed/expected ratio (o/e) 0.9, 90% interval 0.84 to 0.96. Synonymous variants: 261 observed, 289.21 expected, observed/expected ratio (o/e) 0.9, 90% interval 0.81 to 1.
Homologues: Orthologues: chimpanzee APCDD1 (99% identical), macaque APCDD1 (99% identical), rabbit APCDD1 (94% identical), rat Apcdd1 (93% identical), mouse Apcdd1 (92% identical), pig APCDD1 (87% identical), dog APCDD1 (87% identical), guinea pig APCDD1 (87% identical), tropical clawed frog apcdd1 (74% identical), zebrafish APCDD1 (54% identical). Paralogues in human: APCDD1L (45% identical).
Diseases named in the same sentence as APCDD1 in open-access papers:
APCDD1 is named in the same sentence as 46 diseases in open-access papers, as found by Europe PMC text mining. Sharing a sentence is not in itself a finding about the gene and the disease. The quoted sentences say what the papers report.
colon cancer (6 papers, 2012 to 2024). "It has been demonstrated that the methylation of WNT target genes (including APCDD1) could be serve as reliable biomarkers for predicting recurrence in colon cancers." (PMID 38327746, 2024). "Ultimately, specific methylation markers (PCDH20, APCDD1, and COCH) were identified as effective markers for identifying cluster that would benefit from immunotherapy in colon cancers." (PMID 38327746, 2024). "Ten RNAs were finally obtained related to colon cancer, which were hsa-miR-2682-5p, hsa-miR-1277-3p, ANGPTL1, SLC22A18AS, FENDRR, PHLPP2, hsa-miR-302a-5p, APCDD1, MEX3A and hsa-miR-509-3-5p." (PMID 36101384, 2022). "Previously, we have shown that methylation of the WNT target genes APCDD1, AXIN2 and DKK1 predicts poor prognosis in stage II colon cancer patients." (PMID 34068407, 2021). "A translational clinical study was conducted, investigating the effect of pre-operative decitabine on the methylation and expression of WNT target genes APCDD1, AXIN2 and DKK1 and global methylation in colon cancer patients." (PMID 34068407, 2021). "The primary objective of this study was to assess whether pre-operative treatment with decitabine can decrease methylation and increase the expression of WNT target genes APCDD1, AXIN2 and DKK1 in colon cancer patients." (PMID 34068407, 2021). "APCDD1 was noted because: (i) its super-enhancer intensity ranked No.2 in SKNMC cells; (ii) it was specifically upregulated in EWS cells and (iii) it has been identified as a tumor-promoting factor in colon cancer." (PMID 30496486, 2019). "Furthermore, we found beneficial-cluster of specific methylation markers (PCDH20, APCDD1, COCH) that could be used in conjunction with microsatellite status to expand the pool of colon cancer patients eligible for immunotherapy." (PMID 38327746, 2024).
hypotrichosis simplex (4 papers, 2014 to 2024). Hypotrichosis simplex (HS) or hereditary hypotrichosis simplex (HHS) is characterized by reduced pilosity over the scalp and body (with sparse, thin, and short hair) in the absence of other anomalies. "APCDD1 is an inhibitor of the Wnt signaling pathway that is abundantly expressed in human hair follicles, and its mutations lead to hereditary hypotrichosis simplex, which is a rare autosomal dominant form of hair loss." (PMID 39056788, 2024). "Previous studies have reported many casual genes associated with heredity hypotrichosis simplex such as LSS, CDSN, and APCDD1, while other studies highlighted that CDH3 variants cause hypotrichosis simplex with juvenile macular dystrophy (HJMD; OMIM #601553) that is manifested later in life." (PMID 35962736, 2022).
Ewing sarcoma (3 papers, 2019 to 2023). A small round cell tumor that lacks morphologic, immunohistochemical, and electron microscopic evidence of neuroectodermal differentiation. "In addition, we identified the super-enhancer-associated APCDD1, which was uniquely expressed at high levels in Ewing sarcoma, as a novel pro-growth gene transcriptionally activated by MEIS1 and EWS-FLI1 in a co-operative fashion." (PMID 30496486, 2019). "Similar to MEIS1 silencing, APCDD1 depletion reduced cell proliferation and anchorage-independent growth of Ewing sarcoma cells." (PMID 30496486, 2019). "Further investigation based on the biological attributes of super-enhancers identified MEIS1 as a novel oncogenic transcription factor that played a key pro-survival role in Ewing sarcoma, via activating the transcription of APCDD1 cooperatively with EWS-FLI1." (PMID 30496486, 2019). "Moreover, our data suggested that MEIS1 and EWS-FLI1 co-operatively activate APCDD1 transcription, thereby promoting the malignant phenotype of Ewing sarcoma cells." (PMID 30496486, 2019). "In Ewing sarcoma, for instance, transcription factor MEIS1 was identified as a super-enhancer-associated gene, which co-operates with EWS-FLI1 oncoprotein to directly co-bind super-enhancer regions of APCDD1, and activates the transcription of APCDD1, thereby inhibiting cell apoptosis." (PMID 36834999, 2023). "Moreover, APCDD1 depletion potently inhibited the growth of Ewing sarcoma xenografts." (PMID 30496486, 2019). "In this study, we showed that APCDD1 knockdown increased the expression of CDC25A, LRP6, LEF1 and NKD1, which are confirmed targets of the canonical Wnt pathway in Ewing sarcoma, implying that APCDD1 might act as a Wnt inhibitor in this cancer." (PMID 30496486, 2019).
alopecia (2 papers, 2019 to 2024). Hair loss usually from the scalp. "The APCDD1 gene inhibits the WNT signaling pathway (WIF1), ultimately interfering with BMP, Eda, and Notch pathways, and this aberration causes alopecia and hair loss." (PMID 30993080, 2019). "Our prioritization approach has found 12 potential physiological biomarkers of alopecia connected with other vital proteins including SHH and APCDD1." (PMID 30993080, 2019).
breast carcinoma (2 papers, 2022 to 2023). "For APCDD1, there is a study that suggested that APCDD1 regulated breast cancer progression by targeting canonical WNT signaling and modulating breast cancer cell invasion." (PMID 36101384, 2022).
keloid (2 papers, 2024 to 2025). An irregularly shaped, elevated mark on the skin caused by deposits of excessive amounts of collagen during wound healing. "The pseudo‐time trajectory axis revealed terminal states at POSTN+ mesenchymal fib and APCDD1+ secretory papillary fib, indicating two distinct differentiation pathways from normal skin to keloids." (PMID 39902627, 2025). "Following the pseudotime of fibroblasts from Fs0 to Fs1 or from normal scars to keloids, the gene expression levels of APCDD1 (a papillary dermal fibroblast marker) and CCL19 (a pro-inflammatory marker) were observed in the beginning and were seen to decrease gradually thereafter." (PMID 38254097, 2024).
autism (1 paper, 2022). Persistent deficits in social interaction and communication and interaction as well as a markedly restricted repertoire of activity and interest as well as repetitive patterns of behavior. "Cg06825512 is annotated to APCDD1 (APC Down-Regulated 1), an inhibitor of the Wnt signaling pathway that has previously been linked to autism." (PMID 33494854, 2022).
autism spectrum disorder (1 paper, 2022). A spectrum of developmental disorders that includes autism, and Asperger syndrome. "Interestingly, both APCDD1 and SPSB4 have previously been linked to autism spectrum disorder in clinical settings." (PMID 33494854, 2022).
autoimmune encephalitis (1 paper, 2023). Inflammation of the brain secondary to an immune response triggered by the body itself. "In the context of demyelinating disease, APCDD1 is increased in endothelial cells in mice with experimental autoimmune encephalitis, and APCDD1 protein and APCDD1 mRNA are increased in human multiple sclerosis (MS) lesions." (PMID 37155902, 2023).
congenital heart disease (1 paper, 2026). A heart disease that is present at birth. "In addition, we applied GSG to an in-house human fetal heart dataset, revealing anatomically coherent spatial domains and identifying APCDD1 as an endocardial-specific marker potentially involved in congenital heart disease." (PMID 42178226, 2026).
dysplasia (1 paper, 2025). A usually neoplastic transformation of the cell, associated with altered architectural tissue patterns. "When we examined differential gene expression across these clonal populations, we identified a distinct transcriptional signature in the dysplasia origin clone, with several genes including TPM2, FAU, PCBD1, and APCDD1 showing consistent upregulation." (PMID 41360789, 2025).
female infertility (1 paper, 2021). Diminished or absent ability of a female to achieve conception. "APCDD1 is involved in adipogenic differentiation, CTDSP2 is a target gene of FOXO and regulates cell cycle progression, EZH2 is an important regulator in the female reproductive tract, MGA4A is involved in embryo lethality and female infertility, and RHOQ regulates mitochondrial function." (PMID 34639162, 2021).
osteosarcoma (1 paper, 2022). A usually aggressive malignant bone-forming mesenchymal neoplasm, predominantly affecting adolescents and young adults. "In osteosarcoma, DNMT3A promotes APCDD1 promoter DNA hyper-methylation, downregulates its expression, and promotes cell invasion and metastasis." (PMID 36059626, 2022).
periodontitis (1 paper, 2025). An acute or chronic inflammatory process that affects the tissues that surround and support the teeth. "Previous studies have reported heterogeneity in gingival fibroblasts in periodontal tissues, with four subsets significantly altered in periodontitis: Fib 1.1 (CXCL1, CXCL2, CXCL13); Fib 1.2 (APCDD1, IGFBP2, MRPS6); Fib 1.3 (APOD, GSN, CFD); and Fib 1.4 (TIMP3, ASPN, COL11A1)." (PMID 40801798, 2025).
prostate carcinoma (1 paper, 2010). A carcinoma that arises from epithelial cells of the prostate gland. "Almost all known transcription targets activated by the Wnt/β-catenin pathway, e.g. CTNNB1, CCCNDs, MMPs, PITX2, CD44, APCDD1, JUN, remain unchanged or are down-regulated in prostate cancer tissue or cell lines compared to normal tissue or cell line." (PMID 20454608, 2010).
Stroke (1 paper, 2012). Sudden impairment of blood flow to a part of the brain due to occlusion or rupture of an artery to the brain. "For stroke, Apcdd1, Atp2b2, Axin2, ITIH-5 and Slc1a1 are specifically expressed in brain vasculome." (PMID 23285140, 2012).
cancer (22 papers, 2014 to 2025). A tumor composed of atypical neoplastic, often pleomorphic cells that invade other tissues. "Application of the FCVPPv2 on a CRC-affected family identified a novel missense variant in the APCDD1 gene and a 5′UTR variant in the HDAC5 gene as potentially cancer predisposing." (PMID 33673279, 2021). "Variants in the APCDD1, CYBA, PTK7 and SRC genes were identified in more than one family, and they were shown to dysregulate basic cellular functions, potentially leading to cancer development." (PMID 41469725, 2025). "Since the APCDD1 gene has been linked to CRC by being involved in the Wnt signaling pathway as a direct target of the beta-Catenin/TCF4 complex, the associated variant (p.R299H) was prioritized as the top cancer-predisposing candidate of all identified missense variants." (PMID 33673279, 2021). "Immediately, we analyzed the expression of the top three genes, which tie for first place (HOXC6, APCDD1, and ASCL2) in multiple cancer types to explore possible roles of the genes in carcinogenesis." (PMID 35774798, 2022). "Among the cancer-specific states, we identified a stem-like state absent in the healthy colon, characterized by upregulation of WNT antagonists, including NOTUM, NKD1, and APCDD1." (PMID 40393458, 2025).
tumor (15 papers, 2019 to 2025). "Moreover, ASCL2 was highly expressed in COAD compared with HOXC6 and APCDD1 in multiple tumor types." (PMID 35774798, 2022). "Moreover, APCDD1, another super-enhancer-associated gene, acting as a downstream target of both MEIS1 and EWS-FLI1, is also characterized as a novel tumor-promoting factor in this malignancy." (PMID 30496486, 2019). "Analysis of leading-edge genes within the NR signature identified five consensus differentially expressed NRs in the two discovery cohorts, all expressed at a significantly higher level in LI versus LD tumours—AXIN2, NKD1, APCDD1, NOTUM and DKK4." (PMID 31563876, 2020). "Among these features, seven were clinical: pathological stage, new tumor event, age, number of lymph nodes, chemotherapy, number of positive lymph nodes, and ethnicity; and four were biological features: hsa-miR-495-3p, WDR77, E2F8, and APCDD1." (PMID 41401030, 2025). "In addition to regions exhibiting fetal tumor characteristics, we also identified areas with embryonal tumor features in this tissue, characterized by high levels of WNT target genes such as NOTUM, DKK1/4, NKD1, APCDD1." (PMID 39567475, 2024). "Strikingly, they found that ligand-dependent tumours tend to silence genes encoding Wnt antagonists, such as AXIN2, NKD1, APCDD1, NOTUM, and DKK4, whereas ligand-independent tumours effectively bypass Wnt-pathway negative feedback loops without the need for such selective pressure." (PMID 33673710, 2021). "The expression of the APC down-regulated 1 (APCDD1) gene, an inhibitor of the Wnt pathway that is frequently activated in HGOS, was also demonstrated to be down-regulated through hypermethylation of its promoter in HGOS, with a consequent enhancement of tumor invasion and metastatic properties." (PMID 32295254, 2020).
APCDD1 also shares sentences with these, for which no sentence is quoted: adenoma (4 papers); ovarian carcinoma (4); colorectal cancer (3); Autoimmunity (1); demyelinating disease (1); endometrial stromal sarcoma (1); familial colorectal cancer (1); fibrosarcoma (1); gynecological cancer (1); histiocytic sarcoma (1); hypotrichosis (1); injury (1); islet cell adenoma (1); islet cell carcinoma (1); leiomyosarcoma (1); liposarcoma (1); lymphoma (1); melanoma (1); multiple sclerosis (1); neuroendocrine tumors (1); non-Hodgkin ́s lymphomas (1); ovarian tumor (1); pancreatic neuroendocrine tumor (1); rhabdomyosarcoma (1); sarcoma (1); serous ovarian cancer (1); soft tissue sarcoma (1); thyroid disease (1).